SCYGR4 (small cysteine and glycine repeat containing 4)
Description:
In the hair cortex, hair keratin intermediate filaments are embedded in an interfilamentous matrix, consisting of hair keratin-associated proteins (KRTAP), which are essential for the formation of a rigid and resistant hair shaft through their extensive disulfide bond cross-linking with abundant cysteine residues of hair keratins. The matrix proteins include the high-sulfur and high-glycine-tyrosine keratins.
Synonyms: KRTAP28-4
Gene: Protein-coding gene on chromosome 2 (227,617,498 to 227,617,815, forward strand). Ensembl gene ENSG00000284631.
Homologues: Orthologues: pig SCYGR4 (82% identical), dog SCYGR4 (80% identical).